RPE65 (retinoid isomerohydrolase RPE65)
Description:
Critical isomerohydrolase in the retinoid cycle involved in regeneration of 11-cis-retinal, the chromophore of rod and cone opsins. Catalyzes the cleavage and isomerization of all-trans-retinyl fatty acid esters to 11-cis-retinol which is further oxidized by 11-cis retinol dehydrogenase to 11-cis-retinal for use as visual chromophore. Essential for the production of 11-cis retinal for both rod and cone photoreceptors. Also capable of catalyzing the isomerization of lutein to meso-zeaxanthin an eye-specific carotenoid. The soluble form binds vitamin A (all-trans-retinol), making it available for LRAT processing to all-trans-retinyl ester. The membrane form, palmitoylated by LRAT, binds all-trans-retinyl esters, making them available for IMH (isomerohydrolase) processing to all-cis-retinol. The soluble form is regenerated by transferring its palmitoyl groups onto 11-cis-retinol, a reaction catalyzed by LRAT (By similarity).
Synonyms: LCA2; rd12; BCO3; RP20; mRPE65; p63; sRPE65
Tractability: Small molecule: a drug acting on it is in phase 2 or 3 trials. Antibody: UniProt places it where antibodies can reach, with high confidence; its Gene Ontology location is reachable by antibodies, with high confidence. Other modalities: an approved drug acts on it.
Target class: Enzyme; Hydrolase
Gene: Protein-coding gene on chromosome 1 (68,428,822 to 68,451,103, reverse strand). Ensembl gene ENSG00000116745.
Subcellular location: Cytoplasm; Cell membrane; Microsome membrane
Pathways (Reactome):
Sensory Perception: The canonical retinoid cycle in rods (twilight vision)
Gene Ontology:
Molecular function: all-trans-retinyl-ester hydrolase, 11-cis retinol forming activity; all-trans-retinyl-palmitate hydrolase, 11-cis retinol forming activity; isomerase activity; protein binding; beta-carotene 15,15'-dioxygenase activity; cardiolipin binding; phosphatidylcholine binding; phosphatidylserine binding; retinol isomerase activity; oxidoreductase activity, acting on single donors with incorporation of molecular oxygen, incorporation of two atoms of oxygen
Biological process: detection of light stimulus involved in visual perception; retina homeostasis; retinoid metabolic process; zeaxanthin biosynthetic process; retinal metabolic process; visual perception; vitamin A metabolic process; camera-type eye development; circadian rhythm; neural retina development; olefinic compound metabolic process; response to light stimulus; retinol metabolic process
Cellular component: endoplasmic reticulum membrane; plasma membrane; cytoplasm; membrane; cell body; nucleus
Genetic constraint (gnomAD): Loss-of-function variants: 58 observed, 72.34 expected, observed/expected ratio (o/e) 0.8, 90% interval 0.65 to 1. The upper end of that interval is the gene's LOEUF score, 1, which puts it in group 4 of 6, group 1 being the genes least tolerant of losing a copy. Missense variants: 643 observed, 663.57 expected, observed/expected ratio (o/e) 0.97, 90% interval 0.91 to 1.03. Synonymous variants: 220 observed, 235.11 expected, observed/expected ratio (o/e) 0.94, 90% interval 0.84 to 1.05.
Gene-disease validity (ClinGen):
ClinGen rates the evidence that RPE65 causes each of these diseases.
RPE65-related recessive retinopathy (autosomal recessive): Definitive. A retinopathy, which may include conditions described as retinitis pigmentosa and Leber congenital amaurosis, caused by biallelic variants in the RPE65 gene.
RPE65-related dominant retinopathy (autosomal dominant): Strong. A retinopathy caused by a heterozygous gain of function variant in the RPE65 gene.
Homologues: Orthologues: chimpanzee RPE65 (100% identical), macaque RPE65 (99% identical), pig RPE65 (99% identical), dog RPE65 (99% identical), rabbit RPE65 (98% identical), rat Rpe65 (94% identical), mouse Rpe65 (94% identical), tropical clawed frog rpe65 (82% identical), guinea pig RPE65 (79% identical), zebrafish rpe65c (75% identical), zebrafish rpe65b (74% identical), zebrafish rpe65a (74% identical). Paralogues in human: BCO2 (41% identical), BCO1 (38% identical).
Diseases named in the same sentence as RPE65 in open-access papers:
RPE65 is named in the same sentence as 109 diseases in open-access papers, as found by Europe PMC text mining. Sharing a sentence is not in itself a finding about the gene and the disease. The quoted sentences say what the papers report.
Leber congenital amaurosis (211 papers, 2007 to 2026). Leber congenital amaurosis (LCA) is a retinal dystrophy defined by blindness and responses to electrophysiological stimulation (Ganzfeld electroretinogram (ERG)) below threshold, associated with severe visual impairment within the first year of life. "For instance, Leber congenital amaurosis (caused by RPE65 mutations has been successfully addressed." (PMID 41805095, 2026). "RPE65-associated Leber congenital amaurosis (LCA) is the only hereditary retinal dystrophy the the U.S. Food and Drug Administration (FDA) has approved for treatment at present." (PMID 40725503, 2025). "It represents the most effective approach for gene therapy targeting the RPE, as demonstrated by the clinical success of voretigene neparvovec in RPE65-associated Leber congenital amaurosis." (PMID 41301509, 2025). "Patients with the RPE65 mutation in Leber congenital amaurosis were associated with ERM (p = 0.019)." (PMID 40725401, 2025). "For example, Leber’s amaurosis is caused by a mutation in the RPE65 gene, which is expressed exclusively in the retinal pigment epithelium." (PMID 41304828, 2025). "A major breakthrough came in 2017 with the approval of Luxturna, an AAV2-based therapy for biallelic RPE65-associated Leber congenital amaurosis (LCA), marking the first successful clinical translation of AAV in IRDs." (PMID 40723812, 2025). "For example, in the case of Leber’s congenital amaurosis (LCA) caused by RPE65 deficiency, early studies using AAV vector therapy improved visual function in some patients, but the duration of efficacy was limited by the progression of retinal degeneration." (PMID 41244789, 2025). "More recently, subretinal injections were used in clinical trials for gene therapy for retinal dystrophies including Leber Congenital Amaurosis (LCA) due to biallelic mutations in the RPE65 gene." (PMID 38700998, 2025). "The approval of voretigene neparvovec (Luxturna) for RPE65-associated Leber congenital amaurosis demonstrated that direct gene supplementation can restore visual function in humans." (PMID 41301509, 2025). "Mutations in LRAT or RPE65 are associated with Leber congenital amaurosis, and variants in RDH5 lead to fundus albipunctatus." (PMID 40365019, 2025). "In RPE65-deficient models of Leber congenital amaurosis, subretinal administration of compacted DNA nanoparticles restored visual cycle activity and improved retinal function." (PMID 41301509, 2025). "Mutations in the RPE65 gene are associated with Leber Congenital amaurosis, characterized by progressive retinal photoreceptor cell degeneration and eventually severe vision loss." (PMID 40137463, 2025). "The first FDA-approved gene therapy for IRDs was used to treat Leber Congenital Amaurosis (LCA) caused by RPE65 mutations." (PMID 39439625, 2024). "AAV has been employed as a vector to deliver the corrected version of the RPE65 gene, which is mutated in both animals and humans with Leber congenital amaurosis, a disease that leads to blindness." (PMID 39456800, 2024). "Voretigene neparvovec (Luxturna®) is the first approved gene therapy for RPE65-linked Leber congenital amaurosis (LCA)." (PMID 37768368, 2024). "RPE65 mutations have been identified in Leber congenital amaurosis and adult-onset retinitis pigmentosa." (PMID 38548946, 2024). "Luxturna (voretigene neparvovec-rzyl) is currently the only gene therapy in ophthalmology approved by both the FDA and the EU for the treatment of patients with Leber congenital amaurosis caused by mutations in the RPE65 gene." (PMID 39456800, 2024). "A notable breakthrough is the approval of Luxturna (voretigene neparvovec), which targets Leber congenital amaurosis caused by mutations in the RPE65 gene." (PMID 39439625, 2024). "In 2017, Luxturna, an AAV2 vector gene therapy, received FDA approval for addressing Leber congenital amaurosis attributed to RPE65 mutations." (PMID 37766208, 2023).
Leber congenital amaurosis (continued). "The Food and Drug Administration’s (FDA) landmark approval of voretigene neparvovec for RPE65-associated Leber Congenital Amaurosis (LCA) stimulated tremendous optimism regarding retinal gene therapy for other monogenic IRDs." (PMID 37762059, 2023). "Most notably, the slowing down of retinoid recycling, as evidenced by retinosome accumulation, is reminiscent of the RPE defect associated with mutations in the visual cycle protein RPE65, which causes Leber congenital amaurosis." (PMID 37768732, 2023). "Mutations in the RPE65 gene are also associated with a severe form of retinitis pigmentosa known as Leber congenital amaurosis (LCA) or severe early childhood-onset retinal dystrophy (SECORD)." (PMID 37893030, 2023). "The RPE65 gene is responsible for vitamin A metabolism in the visual cycle, and its mutation causes the syndrome of Leber congenital amaurosis (LCA)." (PMID 36840007, 2023). "In patients affected by Leber’s congenital amaurosis and RP caused by mutations in the RPE65 gene, successful gene therapy clinical trials have been completed, in which a viral vector containing the RPE65 transgene was injected into the subretinal space." (PMID 35456263, 2022). "RPE65-linked IRD account for about 3–16% of Leber congenital amaurosis (LCA2) and approximately 0.6–6% of retinitis pigmentosa (RP20)." (PMID 36672611, 2022). "Leber congenital amaurosis is caused by mutations in RPE65 and leads to retinal degeneration in children." (PMID 35383196, 2022). "Leber congenital amaurosis caused by mutations in the RPE65 gene belongs to the most severe early-onset hereditary childhood retinopathies naturally progressing to legal blindness." (PMID 36672611, 2022). "The safety of an adeno-associated virus (AAV) carrying Retinoid Isomerohydrolase RPE65 (RPE65) cDNA for treating Leber’s congenital amaurosis (LCA) has been investigated and the results showed that the treatment does not pose any major adverse effect." (PMID 35052837, 2022). "In 2017, the United States Food and Drug Administration (FDA) approved Voretigene Neparvovec (Luxturna), an adeno-associated virus (AAV) vector-based therapy for patients with biallelic RPE65 mutation-associated Leber congenital amaurosis (LCA)." (PMID 35205388, 2022). "This is best illustrated with the first adeno-associated virus (AAV)-based gene therapy in the treatment of mutated retinoid isomerohydrolase 65 (RPE65) in Leber congenital amaurosis-2 (LCA-2)." (PMID 35467460, 2022). "Though RPE65 variants cause recessive Leber congenital amaurosis, this variant has a unique effect and is the only RPE65 variant known to cause a choroideremia-like appearance." (PMID 33776059, 2021). "One RCT and five NRSIs were assessed, all for adeno-associated virus two (AAV2)-mediated treatment of RPE-specific 65 kDa (RPE65)-associated LCA (Leber congenital amaurosis)." (PMID 34069580, 2021). "Gene therapy is approved for four disorders: beta‐thalassemia, spinal muscular atrophy, adenosine deaminase deficiency, and RPE65‐related Leber congenital amaurosis." (PMID 33350578, 2021). "Until now, more than 260 genes and loci related to retinal diseases such as RPE65-Leber congenital amaurosis (RPE65-LCA) and X-linked juvenile retinoschisis have been mapped in a genetic database." (PMID 34200993, 2021). "Over 2 decades, at least five different adeno-associated virus (AAV)-RPE65 products were tested using mouse and canine models of Leber congenital amaurosis 2 (LCA2), which led to a total of 13 clinical trials." (PMID 34778871, 2021). "Luxturna, the first Food and Drug Administration (FDA)-approved ocular gene therapeutic product was developed to treat Leber congenital amaurosis (LCA) patients with bi-allelic mutations in the RPE65 gene." (PMID 33917548, 2021). "On the other hand, RPE65 bi-allelic mutations cause Leber congenital amaurosis (LCA), which can also lead to RP." (PMID 34440922, 2021).
Leber congenital amaurosis (continued). "For example, nystagmus associated with episodic ataxia type 2 caused by CACNA1A pathogenic variant can be ameliorated with acetazolamide, and Leber congenital amaurosis caused by bi-allelic RPE65 variants can be treated with gene therapy." (PMID 35052368, 2021). "It is administered as a subretinal injection in patients with biallelic RPE65 gene mutations, suffering from Leber’s congenital amaurosis (eye disease, NCT00999609)." (PMID 32803721, 2021). "Another approach for CRISPR/Cas9 based gene therapy corrected a nonsense mutation in Rpe65 that is associated with Leber congenital amaurosis (LCA)." (PMID 34199901, 2021). "Since the US Food and Drug Administration approved gene therapy for Leber’s congenital amaurosis with biallelic RPE65 variants in December 2017, genetic testing has gained greater attention." (PMID 35052368, 2021). "Recently, however, the Food and Drug Administration approved gene therapy for the treatment of RPE65-related Leber congenital amaurosis in patients with RPE65 mutations after gene replacement demonstrated improvement of functional vision." (PMID 33809186, 2021). "This has been demonstrated by the approval of the first gene supplementation therapy to treat an autosomal recessive IRD, RPE65-linked Leber congenital amaurosis (type 2), 4 years ago." (PMID 34660621, 2021). "Leber Congenital Amaurosis (LCA) is caused by mutant RPE65 impacting the isomerization of all-trans retinol to 11-cis retinol, leading to childhood blindness." (PMID 34836244, 2021). "RPE65 is essential for vision, and mutations in rpe65 genes induce Leber congenital amaurosis, a form of retinitis pigmentosa that leads to blindness." (PMID 32183063, 2020). "Supplementation of the retinal pigment epithelium-specific 65 kDa protein (RPE65) gene in patients with Leber congenital amaurosis due to RPE65 mutations improves their light sensitivity and performance in the multi-luminance mobility test." (PMID 32719682, 2020). "Defects of RPE65 have been known to cause a type of autosomal recessive RP or Leber congenital amaurosis (LCA), which is a type of early-onset RP that occurs in children." (PMID 31781647, 2019). "Clinical trials using gene augmentation therapy led to promising results in a subgroup of Leber congenital amaurosis (LCA) that is caused by mutations in the RPE65 gene." (PMID 31842393, 2019). "RPE65-associated Leber congenital amaurosis (LCA) is one of highly heterogeneous, early onset, severe retinal dystrophies with at least 130 gene mutation sites identified." (PMID 31572124, 2019). "Mutations of the gene coding for RPE65 result in the impairment of the visual cycle and cause retinal dystrophies, such as Leber congenital amaurosis (LCA) and retinitis pigmentosa (RP)." (PMID 30695025, 2019). "Several pathogenic variants have already been described in the RPE65 gene which lead to childhood retinal dystrophy, ranging from Leber congenital amaurosis (LCA) to early-onset retinal dystrophy (EORD)." (PMID 31878136, 2019). "Mutations of RPE65 cause the retinal degeneration, Leber congenital amaurosis, and retinitis pigmentosa." (PMID 30937396, 2019). "RPE65 is a well-studied gene with mutations known to cause AR Leber congenital amaurosis (LCA) and retinitis pigmentosa (RP)." (PMID 30477545, 2018). "A successful example of this is the retinal gene therapy (Luxturna), which has been successfully developed for RPE65-associated Leber congenital amaurosis." (PMID 29487844, 2018). "Adeno-associated viral (AAV) vector based gene therapy for RPE65-associated Leber congenital amaurosis (LCA) and choroideremia (CHM) have entered Phase III and II clinical trials respectively." (PMID 28820183, 2017). "Mutations in RPE65 are associated with several retinal disorders, including retinitis pigmentosa (RP), Leber congenital amaurosis (LCA), and early-onset retinal dystrophy (RD) in children." (PMID 29038159, 2017).